Y_RNA (Y RNA )
Gene: Miscellaneous RNA gene on chromosome X (3,641,443 to 3,641,555, reverse strand). Ensembl gene ENSG00000207320.
Homologues: Orthologues: chimpanzee Y_RNA (99% identical). Paralogues in human: Y_RNA (87% identical), Y_RNA (85% identical), Y_RNA (82% identical), Y_RNA (81% identical), RNY1 (81% identical), Y_RNA (80% identical), RNY1P11 (79% identical), RNY1P2 (79% identical), Y_RNA (79% identical), Y_RNA (78% identical), RNY1P5 (77% identical), Y_RNA (77% identical), and 95 more.